ROS1 (ROS proto-oncogene 1, receptor tyrosine kinase)
Diseases named in the same sentence as ROS1 in open-access papers (continued):
Sharing a sentence is not in itself a finding about the gene and the disease.
tumor (continued). "Patient CRUK0056 was not a candidate to receive targeted therapies since her tumour was classified as stage IB and she did not harbour any mutation associated to known driver genes (e.g., EGFR, ALK, ROS1, BRAF, RET)." (PMID 31540260, 2019). "Secondly, data on EGFR mutational status was only available for 42 (77.8%) patients and no data was available on other tumor mutations (e.g. ALK, ROS1, BRAF) for which targeted treatments now exist." (PMID 30973926, 2019). "Detecting tumor markers such as EGFR, ALK, ROS1, and PDL-1 in the blood or plasma might not only guide management, but also detect early therapy resistance, relapse, and establish a prognosis." (PMID 31818027, 2019). "In most cases of ROS1-rearranged NSCLC, crizotinib induces marked tumor shrinkage." (PMID 31399568, 2019). "Six genes were found to be altered in two tumours: MYO1A, DNAH11, SH2D5, ATM, MUC4 and ROS1." (PMID 29665859, 2018). "In patient P2, ROS1 p.I1967V levels in plasma DNA dramatically decreased after a surgical operation, which is indicative of tumor removal; however, this was not reflected in the MP/KRAS and MP/FNA." (PMID 30072705, 2018). "Amongst these tumours, ROS1 rearrangements never overlap with ALK fusions, and rarely co-occurr with oncogenic EGFR mutations (0.5%; 1/220) or KRAS mutations (1.8%; 4/220)." (PMID 29455670, 2018). "The tumor was tested by immunohistochemistry (IHC) for TRKA, ROS1 and ALK proteins whose expression may indicate the result of a genetic alteration." (PMID 28903424, 2017). "Oncogenes ALK, ROS1, RET and MET have been characterized as indicators for tumor growth." (PMID 28716024, 2017). "ROS1 gains, amplifications and deletions, most of them due to chromosome 6 polysomy or monosomy, were heterogeneous within a tumor and had no impact on overall survival." (PMID 26783962, 2016). "ros1 mutants are still able to induce tumor formation but these are a dead end because they do not contain any spores." (PMID 27332891, 2016). "Remarkably, dark pigmented teliospores were absent in the tumors induced by the ros1 deletion strains and softening of the tumor tissue which usually becomes evident when teliospores accumulate in wild type infections did not occur." (PMID 27332891, 2016). "We assessed whether LIPI, in combination with baseline clinical characteristics, can guide first-line treatment selection between pembrolizumab (P) and pembrolizumab plus platinum-based chemotherapy (PCT) in patients with PD-L1 tumor proportion score (TPS) ≥ 50% and EGFR/ALK/ROS1 wild-type." (PMID 40429538, 2025). "This can be exploited by the immunohistochemical detection of oncogenic ROS1 in NSCLC tumor cells; however, recent data have questioned the specificity of the available ROS1 antibodies and advocated for the use of reflex NGS for the detection of ROS1 alterations." (PMID 40075878, 2025). "Following multiple rounds of treatment with pembrolizumab, tumor cells lacking ROS1 rearrangement may be effectively eliminated." (PMID 39723367, 2024). "Although existing transcriptome studies lack the necessary depth and specificity required for a comprehensive characterization of ROS1-driven NSCLC, we hypothesized that reanalysis based on combined data can yield a more representative characterization of this tumor type." (PMID 39737401, 2024). "The ROS1-specific overexpression of NMNAT2, an enzyme involved in nicotinamide adenine dinucleotide (NAD) synthesis, and ISL1, a crucial transcription factor regulating glycolysis and tumorigenesis, highlight the metabolic dependencies of ROS1+ tumor specimens and cell lines." (PMID 39737401, 2024). "The discoveries of tumor-driver genes such as epidermal growth factor receptor (EGFR), anaplastic lymphoma kinase (ALK), mesenchymal-epithelial transition (MET), and c-ros oncogene 1 (ROS1) in NSCLC have recommended TKIs as the first-line option for patients with advanced stage disease." (PMID 38927911, 2024).
tumor (continued). "Studies have shown that MET gene amplification can often coexist with other tumor driver genes in NSCLC, such as EGFR and KRAS mutations and ALK and ROS1 fusions, indicating that MET gene amplification may not act as an intrinsic driver factor within tumors." (PMID 39582541, 2024). "Indeed, ROS1 inhibition by either crizotinib or entrectinib increased FAK-YAP activity and enhanced TRX activity, which decreased oxidative stress-related DNA damage to compromise the anti-tumor effect of the drug treatment." (PMID 37324948, 2023). "However, the tumor response rate to crizotinib in the ALK‐rearranged cohort was also lower in the anticoagulation subgroup than in the non‐anticoagulated subgroup, and a similar trend was also observed in the cohort of ROS1‐rearranged NSCLC." (PMID 35510711, 2022). "Fifth, we did not have information on tumor genetics which may influence the risk of thrombosis, as some oncogenic rearrangements (for example, ALK or ROS1) are more frequent in patients with adenocarcinoma." (PMID 36077663, 2022). "Thus, fusions in ROS1, RET, NTRK1 and amplifications in MET, ALK, EGFR, for example, may not be detected with circulating DNA and RNA, notably during tumor progression under treatment with TKI targeting ALK rearrangements." (PMID 33467720, 2021). "When these tumor-free mice were re-challenged in the opposite flank with the same dose of KL-ROS1 cells, they were protected (not shown), suggesting that anti-ROS1 DNA electrovaccination efficiently induces an immune memory against ROS1 protein-expressing cells." (PMID 32268572, 2020). "Most notably, in cases in which tumour tissues could not be analysed, additional mutations affecting the actionable genes EGFR and ROS1 were detected in BW samples." (PMID 32441866, 2020). "In addition, a case with a ROS1 fusion detected by florescence in situ hybridization analysis showed weak positive cytoplasmic staining in 5% of tumor cells, which was considered as a negative result according to our criteria." (PMID 31234388, 2019). "While application of precision medicine with therapeutics targeting RTKs yields dramatic responses in LUADs bearing oncogenic EGFR, ALK and ROS1, chronic control or cures have not yet been realized due to the inevitability of acquired resistance leading to tumor relapse." (PMID 29458371, 2018). "Thus, CCDC6, when fused to ROS1 and RET kinase, could be imagined as a predictive biomarker of resistance to conventional single mode therapy and provides indications about the tumour sensitivity to PARPi in combination with TKI in NSCLC." (PMID 29455670, 2018). "Currently, however ROS1 testing is often part of a second phase of testing in a patient whose tumour is negative for more common, routinely tested alterations such as EGFR and KRAS mutation and ALK gene rearrangement and who is a lifelong never or long-time ex-smoker." (PMID 27535289, 2016). "Ros1 does not influence the ability of U. maydis to induce tumor formation, but is the key regulator for switching from b-dependent filamentation to hyphal aggregation and spore formation." (PMID 27332891, 2016). "However, there was no distinct correlation between the ROS1 fusion partners and the tumor response of crizotinib treatment." (PMID 27738334, 2016). "Given the rarity of ROS1 rearrangements in NSCLC, screening of tumours by IHC may allow unnecessary FISH analysis in ROS1-negative cases to be avoided and thus dramatically reduce the cost of testing." (PMID 27535289, 2016). "This tumor is negative for ROS1 and ALK gene rearrangement or protein expression (data not shown)." (PMID 26472021, 2015). "However, ROS1 fusion transcripts could not be detected in a post hoc analysis of the tumour RNA using the FusionPlex Expanded Sarcoma Assay." (PMID 38891886, 2024).
tumor (continued). "Simultaneously, subpopulations of tumor cells with ROS1 rearrangement, which were not initially detected, may gradually expand and become the dominant clone within the tumor population due to their resistance to pembrolizumab, thus being discovered in subsequent testing." (PMID 39723367, 2024). "PD-1 and PD-L1 inhibitors are the mainstay of systemic treatment for aNSCLC in patients without therapeutically actionable tumor genomic aberrations, such as epidermal growth factor receptor (EGFR) mutations, anaplastic lymphoma kinase (ALK) translocations or ROS proto-oncogene 1 (ROS1) fusions." (PMID 36008722, 2022). "We have identified a member of the WOPR family of transcription factors, Ros1, as major regulator of spore formation in U. maydis. ros1 expression is induced only late during infection and hence Ros1 is neither involved in plant colonization of dikaryotic fungal hyphae nor in plant tumor formation." (PMID 27332891, 2016). "The ROS1 fusion partner was assessed in 31 out of 50 ROS1+ NSCLC patients with complete clinical data, while 6 additional patients without clinical data had available tumor samples for ROS1 fusion partner evaluation." (PMID 40878657, 2025). "NGS is primarily applied in advanced non-squamous NSCLC, where tumor NGS testing is routinely recommended owing to the presence of numerous actionable genetic alterations, including EGFR, ALK, and ROS1, which can be targeted with specific therapies." (PMID 41515905, 2025). "Moreover, low tumor mitotic activity was associated with better prognosis in LUAD subgroups with EGFR mutations or pan-negative (no oncogenic alteration in genes including KRAS, EGFR, BRAF, ERBB2, PIK3CA, ALK, and ROS1) but not in those with KRAS or BRAF mutations." (PMID 41404730, 2025). "ALK and ROS1 gene rearrangements often show high PD-L1 expression but low TMB, and these tumours are not responsive to ICI treatment." (PMID 38953007, 2024). "Though there is no level 1 evidence due to the rarity of the tumour with dual EGFR and ROS1 positivity, literature supports the use of TKI rather than chemotherapy in such cases." (PMID 38425761, 2024). "Owing to the tendency of ROS1 to be mutually exclusive with genes such as ALK, this study suggests that IHC can be used to screen tumor specimens negative for ALK expression before conducting FISH on specimens with positive IHC results." (PMID 38629293, 2024). "The main driver mutations of primary tumours with LM were determined by NGS, including EGFR L858R (10, 35.7%), EGFR 19del (6, 21.4%), EGFR L858R + MET amplification (1, 3.6%), EGFR L858R+S768I (1, 3.6%), ALK (2, 7.1%), ROS1 (1, 3.6%), negative (5, 17.9%), and unknown (2, 7.1%)." (PMID 38269023, 2023). "Consistent with the idea that there are common mediators of resistance to therapies regardless of tumor type, this case highlights the potential for AXL to also drive intrinsic resistance to ROS1 inhibitors in NSCLC." (PMID 37727007, 2023). "Eligible patients had recorded programmed death-ligand 1 (PD-L1) tumor proportion score (TPS) and no known actionable EGFR/ALK/ROS1/BRAF genomic alteration." (PMID 35740512, 2022). "All these FGFR inhibitors are multi-kinase inhibitors that also exhibit nonspecific anti-tumor activities against other tyrosine kinases, including VEGFR, PDGFR, ROS1, and/or RET." (PMID 33710807, 2021). "One study observed that PET-based radiomics combined with tumor stage and age was able to differentiate ALK/ROS1/RET fusion-positive and fusion negative tumors (sensitivity = 0.73, specificity = 0.70)." (PMID 34208595, 2021). "Additional genetic testing revealed the patient was negative for ALK fluorescence in situ hybridization, ROS1, BRAF, and EGFR and PD-L1 22C3 IHC with Tumor Proportion Score (TPS) of <1%." (PMID 33101670, 2020). "Additional genetic testing revealed the patient was negative for EGFR, ALK fluorescence in situ hybridization, ROS1, BRAF, and PD-L1 22C3 IHC with Tumor Proportion Score (TPS) was less than 1%." (PMID 33101670, 2020).
tumor (continued). "A phase I trial is assessing the pan-TRK, ROS1 and ALK inhibitor entrectinib in paediatric patients with relapsed or refractory solid and Central Nervous System (CNS) tumours with and without TRK, ROS1 and ALK fusions (NCT02650401)." (PMID 29642598, 2018). "In the entire analyzed group, the risk of progression was not significantly related to age, gender, ALK or ROS1 abnormality testing method (IHC vs. FISH vs. NGS), body weight, smoking status, size and location of tumor, CNS and bone metastases, or treatment toxicities." (PMID 40227844, 2025). "Similarly, in the initial RAN classifier, attention maps frequently focused on tumor regions with high nuclear density and architectural complexity, suggesting these features may serve as general indicators of fusion positivity across ROS1, ALK, and NTRK subtypes (heatmaps not shown)." (PMID 40739404, 2025). "In such instances and in cases in which the tumor cellularity is below 10%, reflexing OFA sNGS and Idylla Genefusion-negative cases for ALK and ROS1 fusion detection by FISH and/or IHC may be necessary." (PMID 37628603, 2023). "This is likely due to selection biases as ROS1 fusions may be detected first by FISH and DNA NGS and RNA NGS are likely being employed when the tumor are “pan-negative”." (PMID 37853341, 2023). "When considering results per ethnic subgroup, activating EGFR mutations were detected in 44%, 28% and 14% of non-squamous metastatic NSCLC tumours in Asian, black and white patients, respectively (p = 0.001) and ALK or ROS1 re-arrangement were detected in 22%, 3% and 17%, respectively (p = 0.2)." (PMID 36551542, 2022). "Third, we did not test other tumor’s driver genes, such as KRAS, ALK, ROS1, and BRAF." (PMID 35096585, 2021). "These primary tumor imaging features are not significantly different compared to the ALK+ and ROS1+ NSCLC tumors included in our cohort or compared to prior reports on ALK or ROS1+ tumors." (PMID 32183422, 2020). "The administration of the pembrolizumab molecule as first-line therapy to patients without genomic alterations in the genes EGFR, ALK, ROS1 and BRAF, and for whom 50 % of the tumor cells express PD-L1, has given back IHC a primordial role in the therapeutic care of patients with NSCLC." (PMID 29534030, 2018). "Similar, crizotinib can be administered to patients with ROS1-rearranged NSCLC that do not express ALK or c-Met, as LDK378 (Ceritinib) and AP26113 ALK inhibitors demonstrate clinical efficacy on crizotinib-resistant NSCLC tumours with increased abundance of IGF-1R and ROS proteins." (PMID 26147305, 2015).
cancer (244 papers, 2011 to 2026). A tumor composed of atypical neoplastic, often pleomorphic cells that invade other tissues. "In the case of ROS1 mutations, there is evidence of its involvement in cancer progression through receptor tyrosine kinase signaling, promoting metastasis and chemoresistance." (PMID 39925800, 2025). "Targeted therapy utilizing TKIs that bind to the receptor tyrosine kinase domain of the ROS1 protein has demonstrated effectiveness against cancers harboring these mutations and has been approved for therapeutic use." (PMID 41179684, 2025). "The proto-oncogene ROS1 encodes a receptor tyrosine kinase implicated in a range of cancers affecting both adult and pediatric patients." (PMID 41179684, 2025). "Repotrectinib, a new-generation ROS1 inhibitor, has demonstrated efficacy against various ROS1 fusion-positive cancers and the G2032R mutation." (PMID 38791529, 2024). "The self‐mutation or rearrangement of ROS1 can activate tyrosine kinase, which promotes the proliferation of various malignant tumors." (PMID 38629293, 2024). "It is worthwhile to note that other ROS1 alterations exist in cancer, including overexpression, amplification and splice variants that lead to truncated ROS1 protein that lacks an intracellular domain." (PMID 38347643, 2024). "For example, crizotinib and ceritinib (discussed in the ROS1/ALK section of this paper) have both demonstrated efficacy against MET-mutated cancers." (PMID 38339363, 2024). "ROS1 codes for a receptor tyrosine kinase and is included in Cosmic Cancer Gene Census as containing mutations causally implicated in cancer." (PMID 37867524, 2023). "Anaplastic lymphoma kinase (ALK), hepatocyte growth factor receptor (HGFR/c-Met), and ROS proto-oncogene 1 receptor tyrosine kinase (ROS1) are tyrosine receptor kinases, implicated to be aberrantly expressed in human cancers." (PMID 38144528, 2023). "ROS1 inhibition results in synthetic lethality in CDH1-deficient cancers, but often leads to adaptive resistance." (PMID 37324948, 2023). "The relative frequency of activating ROS1 mutations in cancer is low (< 0.1%); curated data from AACR Genie portal is shown in Fig EV1B." (PMID 37587872, 2023). "Co-treatment of mice with the FAK inhibitor and ROS1 inhibitors also showed synergistic effects against CDH1-deficient cancers." (PMID 37324948, 2023). "FAK inhibition, either by FAK inhibitors or by knocking down its expression, resulted in higher cytotoxicity potency of the ROS1 inhibitor in CDH1-deficient cancer cell lines." (PMID 37324948, 2023). "This suggests that activated ROS1 has the potential to be a pathogenic cancer driver in diverse cancers, aligning with the occurrence of ROS1 fusion oncogenes in a wide range of adult and pediatric cancers." (PMID 37587872, 2023). "In the present study, hyperactivation of FAK signaling was also found to be related to the adaptive resistance to a ROS1 inhibitor in the treatment of CDH1-deficient cancers." (PMID 37324948, 2023). "ROS1 is a receptor tyrosine kinase whose activation is reported to be linked to the growth and proliferation of malignant tumors." (PMID 36589752, 2022). "ADGRG6 can also form carcinogenic fusion variants with ROS1 to promote the development of EGFR-tyrosine kinase inhibitor resistance in cancer patients with EGFR mutation." (PMID 34809653, 2021). "In total, we included 10,967 patients from TCGA and 10,945 patients from MSK, among which 1,661 patients were treated with ICI, for genomic analysis evaluating the prevalence of ROS1 mutation across various cancers." (PMID 34221982, 2021). "Further mutations in cancer-related genes included Nav3 (V1129L), Cenpf (D1327E), Muc5ac (A429P), Mpp7 (Q158R), Gas1 (G326R), Maged2 (A473S), Dusp1 (C24R), Ros1 (W1875C), Polr2a (M1102I), Rragd (L385P), and Hoxa9 (insertion of “G” in UTR)." (PMID 32793490, 2020). "For cancer related genes, Nav3, Cenpf, Muc5Ac, Mpp7, Gas1, MageD2, Dusp1, Ros, Polr2a, Rragd, Ros1, and Hoxa9 are mutated." (PMID 32793490, 2020).